HLA-G (major histocompatibility complex, class I, G)
Diseases named in the same sentence as HLA-G in open-access papers (continued):
Sharing a sentence is not in itself a finding about the gene and the disease.
sarcoidosis (1 paper, 2019). Sarcoidosis is a multisystemic disorder of unknown cause characterized by the formation of immune granulomas in involved organs. "In sarcoidosis, the association with HLA-II is thought to be more important, but it should be noted that limited information exists in relation to HLA-G in sarcoidosis." (PMID 31921204, 2019). "In one study, the HLA-G variation was seen in sarcoidosis patients." (PMID 31921204, 2019).
scoliosis (1 paper, 2025). A congenital or acquired spinal deformity characterized by lateral curvature of the spine. "BACH2 and HLA-G shared the same variant with CD28 on CD28+ CD45RA+ CD8+ T cell which could increase the risk of scoliosis." (PMID 40270514, 2025).
septic shock (1 paper, 2023). Shock caused by infection; frequently caused by gram negative bacteria, although some cases have been caused by other bacteria, viruses, fungi, and protozoa; characterized by fever, chills, tachycardia, tachypnea, and hypotension. "It has been reported that the polymorphic variants associated with exon 8 that are located at the 3 ́-UTR of the HLA-G gene are connected with septic shock that can occur in patients that are critically ill." (PMID 37749550, 2023).
sickle cell disease (1 paper, 2014). Sickle cell anemias are chronic hemolytic diseases that may induce three types of acute accidents: severe anemia, severe bacterial infections, and ischemic vasoocclusive accidents (VOA) caused by sickle-shaped red blood cells obstructing small blood vessels and capillaries. "HLA-G polymorphism may also affect susceptibility to HCV infection in patients with sickle cell disease, because the C allele seems to confer protection against HCV, by a mechanism associated with an increase in HLA-G expression." (PMID 24839609, 2014).
systolic heart failure (1 paper, 2016). Heart failure caused by abnormal myocardial contraction during systole leading to defective cardiac emptying. "This is supported by the observations in the current study, which could indicate that specific HLA-G gene polymorphisms or haplotypes might influence the sHLA-G level in the blood and thereby the individual sHLA-G response in specific patients with systolic heart failure." (PMID 27800497, 2016). "A single published study has indicated that soluble HLA-G (sHLA-G) in plasma is upregulated in patients with systolic heart failure, compared to healthy controls, and independent of NYHA class, EF, and other biomarkers." (PMID 27800497, 2016). "One limitation of the current study is that the number of study participants is rather small; however, it is still the largest study until now regarding HLA-G in subjects with and without systolic heart failure." (PMID 27800497, 2016).
thymoma (1 paper, 2021). A neoplasm arising from the epithelial cells of the thymus. "In addition, higher mRNA levels of HLA-G in STAD (P=0.0044) and thymoma (THYM) (P=0.0026) were significantly associated with shorter OS." (PMID 34276642, 2021).
thyroid autoimmunity (1 paper, 2015). "Possible causes of miscarriage range from thyroid autoimmunity, abnormal HLA-G expression to disrupted paternal genome." (PMID 25649376, 2015).
toxicities (1 paper, 2024). "Liver toxicities have been associated with CRS, but liver inflammation may possibly lead to upregulation of HLA-G in the liver." (PMID 39105878, 2024).
viral hepatitis (1 paper, 2015). An acute or chronic inflammation of the liver parenchyma caused by viruses. "In this study, we revised the role of the molecule and polymorphic sites along the HLA-G gene in tumors, viral hepatitis, and parasitic disorders." (PMID 25699038, 2015).
vulvar squamous cell carcinoma (1 paper, 2024). An invasive squamous cell carcinoma arising from the vulva. "HLA-G protein was highly expressed in vulvar squamous cell carcinoma, which was correlated with clinical stage, tumor size, and tumor invasion depth, and patients with low HLA-G expression had a good prognosis." (PMID 38427106, 2024).
tumor (398 papers, 2006 to 2026). "The tumor microenvironment (TME) of EwS is shaped by immunosuppressive components, including myeloid-derived suppressor cells, tumor-associated macrophages, and immune checkpoint molecules such as PD-1/PD-L1 and HLA-G." (PMID 40242222, 2025). "In patients with GC, previous studies have shown that tumor lesion HLA-G expression is significantly associated with advanced disease stage, susceptibility to immune suppression, disease progression, and poor patient survival." (PMID 41181133, 2025). "We evaluated soluble HLA-G (sHLA-G) levels via ELISA, investigated HLA-G expression loss in tumor samples through immunohistochemistry (IHC), and assessed killer cell immunoglobulin-like receptor (KIR) expression on NK cells in tumor tissues." (PMID 41234446, 2025). "HLA-G expression has been observed in various malignancies and is strongly associated with tumor immune escape, metastasis, and poor prognosis." (PMID 41211166, 2025). "Functionally, both membrane-bound and soluble HLA-G isoforms can impair anti-tumor immune responses and are associated with cancer progression." (PMID 41194925, 2025). "The aim of this study was to investigate the possible roles of innate immunity and associated HLA-G molecules in the development of CRC by examining tumor tissue samples." (PMID 41234446, 2025). "Both tumor cell-associated and soluble HLA-G have been reported in the blood of NSCLC patients, and are associated with advanced TNM stages, suppressed NK-cell-mediated cytolysis, and reduced OS." (PMID 41023740, 2025). "Its impact on immune evasion mechanisms and broad expression, coupled with associations withpoor survival and distinct tumor phenotypes, positions HLA-G as a promising protein for further exploration in developing targeted immunotherapies for MIBC patients." (PMID 39469714, 2024). "We demonstrate, for the first time, that HLA-G modifies key genes implicated mainly in tumor development, angiogenesis, calcium flow and mitochondria dynamics." (PMID 39358558, 2024). "The expression of HLA-G has been observed to be associated with tumor staging, prognosis, and circulating levels in various types of cancer." (PMID 38818502, 2024). "Particularly, HLA-G expression has been associated with advanced disease stages, increased tumor metastasis, worse prognosis and reduced disease-free survival." (PMID 39105878, 2024). "High HLA-G expression in solid cancers has been associated with tumor size, advanced disease, tumor metastasis, and worse survival rates." (PMID 39766165, 2024). "Based on our findings, HLA-G appears to be a promising biomarker associated with the biological characteristics, the composition of the tumor immune microenvironment (TIME), and clinical outcomes in MIBC." (PMID 39469714, 2024). "Prior research has demonstrated an increase in HLA-G expression across diverse tumor entities, which is associated with a poor patients’ prognosis." (PMID 39469714, 2024). "The associations between the HLA-G 14 bp ins/del polymorphism, HLA-G mRNA expression, and/or sHLA-G levels and selected variables including tumor grade, disease stage, body mass index, and heart rate variability (HRV) parameters were evaluated." (PMID 39594832, 2024). "This is validated by recent studies which revealed a similar clinical impact of HLA-G tumor cell expression and an association with shorter overall survival in other tumor entities." (PMID 39469714, 2024). "HLA-G expression promotes tumor progression, metastasis and is associated with poor clinical outcome." (PMID 38707901, 2024). "Considering that HLA-G is limited to immune-privileged tissues and is almost undetectable in normal cells, chemotherapy-induced high expression of HLA-G in tumor cells would cause a further reduction in the damaging effects of HLA-G CAR-NK on normal tissues." (PMID 38310272, 2024).
tumor (continued). "Upregulated expression of HLA-G by virus-infected cell is proposed to inhibit cytolytic action of natural killer cells and T-cells, and this is also associated to tumor growth and disease progression in various types of cancers." (PMID 38398102, 2024). "Human leukocyte antigen-G (HLA-G) is a cancer-associated immune checkpoint protein implicated in tumor-driven immune escape mechanisms." (PMID 39703498, 2024). "Studies have found that increased expression of HLA-G in cancers is associated with advanced tumor stage, metastasis status and poor disease outcomes." (PMID 38391781, 2024). "To understand the contribution of the HLA-G genetic background in PTC, we studied the HLA-G gene variability in PTC patients in association with tumor morbidity, HLA-G tissue expression, and plasma soluble (sHLA-G) levels." (PMID 37629044, 2023). "In the present study, we aimed to address the immune escape caused by PD‐L1 to reinforce the anti‐tumor activity of HLA‐G‐targeted CAR‐T therapy." (PMID 37078788, 2023). "HLA-G possesses a heterogeneous and focal expression pattern, and can be expressed at the cell surface, secreted, or associated with tumor-derived exosomes." (PMID 38067396, 2023). "In GC, HLA-G expression correlates with a Treg cell infiltration associated with tumor progression and a low 5-year overall survival rate." (PMID 37573450, 2023). "HLA-G expression has been closely associated with tumor progression and patient prognosis, making it a promising target for CAR-T cell therapy." (PMID 37627278, 2023). "A large amount of evidence has revealed that HLA-G is strongly linked to tumor angiogenesis, escape, metastasis and survival of patients." (PMID 37875821, 2023). "In the future, there will be a need for additional studies to obtain deeper insight into the association between HLA-G isoforms and cytokines expression profile in tumour microenvironment." (PMID 36053326, 2023). "Human leukocyte antigen G (HLA-G) is another checkpoint molecule involved in tumor immune escape and is strongly associated with increased tumor invasiveness and suppression of immune cell function." (PMID 36212414, 2022). "Consistently, HLA-G expression in various malignancies was associated with tumour escaping immunosurveillance and was also involved in the mechanism of metastasis, leading to poor clinical outcomes." (PMID 35806034, 2022). "Thanks to the ability of tumors to escape from the immune system, the mechanism of “cancer immunoediting” arises, by which immunoresistant tumor variants are generated and in which molecules such as HLA-G participate." (PMID 35154112, 2022). "It has been recently demonstrated that HLA-G is crucial for tumor immune evasion and is also associated with malignant transformation." (PMID 35185904, 2022). "Although aberrant HLA‐G expression has been reported to be associated with advanced tumor stage, metastasis status, and poor disease outcome, some discrepancies remain in various cancer types." (PMID 35759240, 2022). "In tumour cells, expression of HLA-G and loss of CDX2 expression were associated with cancer recurrence." (PMID 35027037, 2022). "Since HLA-G is frequently associated with an advanced tumor stage and a poor prognosis of patients, a diagnostic and prognostic potential has been suggested for HLA-G in different cancer types." (PMID 35185904, 2022). "Several polymorphisms in the 3’UTR region condition changes in HLA-G expression (14bp and +3142C/G, among others), which have been associated with both the development and outcome of patients with different tumor types." (PMID 35154112, 2022). "In cancer, the expression of HLA‐G is heterogeneous and shows high association with an immunosuppressive microenvironment, advanced tumor stage, poor response to treatment, and prognosis." (PMID 35759240, 2022).
tumor (continued). "Regarding the clinicopathological factors, studies showing significant association between tumour HLA-G expression and poor patient survival, also observed positive correlations between HLA-G expression and advanced TNM stages." (PMID 34361031, 2021). "Yet, several clinicopathological factors associated with increased tumour burden were associated with HLA-G expression." (PMID 34361031, 2021). "HLA-G has been reported to be a key molecule in tumor immune tolerance and is associated with poor prognosis in cancer patients." (PMID 34221955, 2021). "Four studies reported on the association between tumour HLA-G expression and clinical outcome of non-small-cell lung carcinoma (NSCLC) patients." (PMID 34361031, 2021). "These two examples indicate that in particular high HLA-G tumour staining associates with clinical parameters." (PMID 34361031, 2021). "A diagram of the proposed mechanism underlying induction of enhanced tumor cell membrane HLA-G expression by low-dose chemotherapy, followed by targeting by HLA-G CAR-NK cells, is shown in." (PMID 34663641, 2021). "Our analysis indicated that HLA-G highly expressed in the tumor microenvironment have positive associations with tumour-infiltrating immune cells, including B cells, CD8+ T cells, CD4+ T cells, macrophages, DCs, and neutrophils." (PMID 34276642, 2021). "In summary, HLA-G expression were not only associated with immune cell infiltration but also showed tumour-promoting and tumour-inhibiting properties." (PMID 34276642, 2021). "Both studies also observed significant associations between HLA-G expression and clinical parameters related to increased tumour burden, such as increased LNM and advanced disease stages." (PMID 34361031, 2021). "Ever increasing studies on HLA-G expression by solid tumor lesions have revealed that high levels of HLA-G expression was associated with advanced disease stage, tumor metastasis, poor prognosis, or shorter disease-free survival." (PMID 34276691, 2021). "If this association cannot be observed, it is unlikely there is a causal relationship between tumour HLA-G expression and inhibition of an anti-tumour immune response." (PMID 34361031, 2021). "As already mentioned, the DEL variant provides greater stability to the HLA-G mRNA, and, hence, yields higher levels of the protein, favoring tumor progression." (PMID 34557189, 2021). "HLA-G expression in solid cancers is now well acknowledged in promoting cancer cell immune escaping and tumor development, and associated with disease progression and poor survival either among cancer patients or pre-clinical murine models." (PMID 34276691, 2021). "Over the last decades, aberrant HLA-G expression has been found in numerous types of cancer, which has been associated with an advanced tumor stage, aggressive transformation and poor disease prognosis." (PMID 34773056, 2021). "In conclusion, several studies demonstrated that tumour HLA-G expression was associated with poor clinal outcome of CRC patients, while other studies that yield more statistical power due to larger sample size did not observe these associations." (PMID 34361031, 2021). "Since already published work showed that this variant increases HLA-G expression, we suggest that patients bearing the DEL allele will extensively display HLA-G, allowing tumor progression." (PMID 34557189, 2021). "Although the data showed that upregulated expression of HLA-G in tumor tissues impacted the prognosis of human tumors, the underlying mechanisms were still unclear." (PMID 34276642, 2021). "Six studies investigated the association between tumour HLA-G expression and clinical outcome of gastric carcinoma (GC) patients." (PMID 34361031, 2021). "Despite these differences, all studies demonstrated significantly poor clinical outcome of patients associated with the highest level of tumour HLA-G expression, either as a single parameter or in conjunction with other immune parameters." (PMID 34361031, 2021).
tumor (continued). "The results showed that HLA-G highly expressed have positive associations with tumor-infiltrating immune cells in the microenvironment in most types of tumors (P<0.05)." (PMID 34276642, 2021). "Nevertheless, increased tumour depth and advanced histological tumour grade were still shown to be associated with tumour HLA-G expression." (PMID 34361031, 2021). "Lastly, not only clinical outcome, but all statistically significant clinicopathological patient and tumour characteristics associated with HLA-G expression were included." (PMID 34361031, 2021). "More importantly, this study demonstrated that NLRP7 knockdown in CC tumor cells was associated with a decrease in the expression of numerous proteins involved in maternal immune tolerance such as HLA-G, PDL1, and hCG." (PMID 34203890, 2021). "14-bp INS/DEL, the most extensively studied polymorphism of HLA-G, has been shown to have a strong association with many tumor types, particularly breast and liver cancer, and is generally indicative of an increased risk of cancer." (PMID 33425752, 2020). "We have to point out that HLA-G expression studies are mainly performed on transfected or transduced tumor cell lines since HLA-G expression is rapidly loss after ex vivo culture or primary tumors." (PMID 32922387, 2020). "HLA-G expression was associated with the clinical tumor stage and lymphatic metastasis.HLA-G level exhibited an inverse correlation with survival rate and a significant direct relationship with clinical stage." (PMID 33425752, 2020). "HLA-G molecule has always been an important immunomodulatory role in cancers and associated with tumor immune escape and poor disease prognosis." (PMID 32123232, 2020). "HLA-G was demonstrated to be crucial for the tumor development and its expression was specifically associated to malignant transformation." (PMID 32922387, 2020). "Loss of classical HLA class I was associated with HLA-G upregulation.IL-10 expression coincided with HLA-G upregulation.NK cells infiltration was associated with loss of HLA class I on tumor cells." (PMID 33425752, 2020). "Despite being an MHC class I molecule, HLA-G is highly present in tumor context and shows unique characteristics of tissue restriction of a Tumor Associated Antigen (TAA), and potent immunosuppressive activity of an Immune CheckPoint (ICP)." (PMID 32922387, 2020). "In this review, we discuss the mechanism underlying HLA-G expression and function, its role played in each step of the tumor-immunity cycle, as well as the potential to target it for therapeutic benefit." (PMID 33425752, 2020). "Both, the expression of IC molecules on peripheral immune cells and soluble forms of HLA-G in the blood are associated with tumor immune escape and consequently discussed as clinical biomarker for disease status and outcome of cancer patients." (PMID 32973812, 2020). "We further explored the correlation between PINK1 expression and representative immune markers in LIHC and LUSC, and PINK1 expression was more strongly correlated with tumor-associated macrophage markers such as HLA-G, CD80, and CD86 in LUSC than in LIHC." (PMID 33244455, 2020). "HLA-G expression is frequently associated with disease progression, tumor metastases, and poor clinical outcome." (PMID 33213057, 2020). "ctopic expression of “tissue-restricted” HLA-G has been detected in many types of malignancies and is frequently associated with advanced tumor stage and poor prognosis in multiple cohorts of patients with cancer." (PMID 33425752, 2020). "In fact, HLA-G expression has been reported in numerous types of cancer, always associated with more advanced stage and aggressive development of the tumor." (PMID 32922387, 2020). "Previous studies indicated that tumor-associated antigen and HLA-G expressed in tumors can promote immune evasion by strongly favoring Th2 development." (PMID 32070368, 2020).